RET (ret proto-oncogene)
Diseases named in the same sentence as RET in open-access papers (continued):
Sharing a sentence is not in itself a finding about the gene and the disease.
lung cancer (continued). "In particular, NTRK3 fusion has achieved post-clinical validation as an acquired resistance mechanism to selpercatinib in RET fusion-positive lung cancer." (PMID 36582799, 2022). "We describe a case of RET fusion-positive lung cancer where molecular targeted therapy and cytotoxic drug showed a drastic response and long-term therapy was well maintained." (PMID 36452495, 2022). "A phase II clinical trial (NCT01639508) reported that RET-fusion positive lung cancer patients receiving cabozantinib (60mg, p.o. daily) demonstrated partial response (28%; 7/25 patients) and fortifies the notion that RET is actionable in lung cancers." (PMID 35957881, 2022). "A study from China used DNA next generation sequencing (NGS) to profile RET fusions in 12,888 lung cancer patients." (PMID 36582799, 2022). "A phase II clinical trial enrolling 26 patients was conducted to determine the efficacy of cabozantinib in metastatic RET fusion-positive lung cancer." (PMID 34497761, 2021). "In essence, a cell viability assay with RET-specific lung cancer cell line LC-2/ad was also carried out to confirm the in vitro biological activity of the resultant compound, DB07194." (PMID 34834190, 2021). "Several clinical studies have demonstrated the efficacy of this drug in specific NSCLC cohorts, in particular in RET-rearranged lung cancer." (PMID 34503226, 2021). "As one of the most selective RET inhibitors, selpercatinib represents a step forward for the management of RET+ lung cancer patients who have been traditionally treated with standard of care therapies." (PMID 34503226, 2021). "Further examination of the response rates for RET fusion-positive lung cancer and treatment strategies for symptomatic brain metastases is critically needed." (PMID 34497761, 2021). "The LIBRETTO-001 and ARROW trials had 11 and nine RET fusion-positive lung cancer patients, respectively, who also had brain metastasis." (PMID 34497761, 2021). "A phase II clinical trial enrolling three patients was conducted to determine the efficacy of sorafenib in metastatic RET fusion-positive lung cancer." (PMID 34497761, 2021). "A phase II investigator-initiated clinical trial (LURET) enrolling 19 patients was conducted in Japan to determine the efficacy of vandetanib in metastatic RET fusion-positive lung cancer." (PMID 34497761, 2021). "Perhaps in future clinical trials of RET fusion-positive lung cancer, selective RET inhibitors will become mainstream." (PMID 34497761, 2021). "In the perspective part, we focused on the unsolved issues on treatment for RET fusion-positive lung cancer and future developments." (PMID 34497761, 2021). "For example, there were some clinical trials with cabozantinib for RET-mutant MTCs and RET fusion-positive lung cancers, but results were underwhelming with considerable side effects." (PMID 34832869, 2021). "Phase II clinical trials enrolling a total of 25 patients were conducted to determine the efficacy of lenvatinib in metastatic RET fusion-positive lung cancer patients in Japan, the United States, Singapore, and Taiwan." (PMID 34497761, 2021). "Pursuing various methods of RET fusion testing, treatment regimens, response results involving various fusion partners, and overcoming drug resistance will allow development of ideal treatment strategies for RET fusion-positive lung cancer patients." (PMID 34497761, 2021). "Some RET fusion-positive lung cancer patients reported from their retrospective perspective that targeted treatment is preferable over treatment with immune checkpoint inhibitors for better prognosis." (PMID 34497761, 2021). "The progression-free survival of RET fusion-positive lung cancer patients treated with multikinase inhibitors including sunitinib, cabozantinib, and vandetanib was reported as 2.2–4.7 months." (PMID 34497761, 2021).
lung cancer (continued). "Since the discovery of RET fusion gene as a new driver gene for lung cancer in 2012, numerous clinical trials have been conducted, and many highly efficacious selective RET inhibitors have been developed." (PMID 34497761, 2021). "Based on this result, the NCCN Guideline (Version 3; 2020) listed vandetanib under Category 2A as an appropriate treatment for metastatic RET fusion-positive lung cancer." (PMID 34497761, 2021). "Anticipating the efficacy of precision medicine for RET fusion-positive lung cancer, domestic and international clinical trials of RET inhibitors have been conducted." (PMID 34497761, 2021). "A randomized phase III trial is currently ongoing for RET fusion-positive lung cancer patients to determine the efficacy of combination therapy with selective RET inhibitors and chemotherapy ± pembrolizumab." (PMID 34497761, 2021). "Lung cancer driver genes mainly include EGFR, ERBB2, MET, RET, ALK, and ROS1, all encoding genes for receptor tyrosine kinases (RTKs)." (PMID 33537237, 2020). "RET can be found in the rearrangement of genes generating RET fusion proteins in many cancers, including lung cancer, and thus an inhibitor was recently approved by the FDA for cancer therapy." (PMID 32235589, 2020). "We further analyzed TCGA data sets to examine the signaling pathways that are activated in lung cancers with RET rearrangements with multiple upstream fusion partners." (PMID 33318047, 2020). "For example, if a lung cancer was found to harbor ret proto-oncogene (RET) fusions, then the cancer can be efficiently treated with Vandetanib, an inhibitor of RET tyrosine kinase." (PMID 33076277, 2020). "More work is required to understand the biology of RET-rearranged lung cancers and to tailor therapeutic strategies." (PMID 32295619, 2020). "In our study here, we developed four new patient-derived lung cancer models with different RET fusions and examined the efficacy of cabozantinib in these models." (PMID 33318047, 2020). "There are also several TKIs available for targeted therapy in advanced lung cancer patients with RET fusions, e.g. selpercatinib, pralsetinib, cabozantinib, and vandetanib." (PMID 33505917, 2020). "Our finding that MYC expression requires continued signaling from RET opens a potentially new avenue for the combinatorial targeting of RET-fusion-driven lung cancers, with RET and new MYC inhibitors to improve response rates." (PMID 33318047, 2020). "The three studies suggested that the incidence of driver gene mutations in NSCLC patient is high, and lung cancer driver genes, such as EGFR, ALK, and RET are risk factors for brain metastasis in advanced NSCLC patients." (PMID 33537237, 2020). "The first RET gene fusion to be detected in lung cancer involved the 3′-end of RET and the 5′-end of the kinesin family member 5B gene (KIF5B)." (PMID 32397295, 2020). "Nevertheless, the role of RET as a tumor suppressor gene has been proven in lung cancer and involved in the progression of colon adenomas to cancer." (PMID 33383911, 2020). "Here, we generated four novel preclinical patient-derived models of RET-rearranged lung cancers and used these models to examine the efficacy of the RET MKI cabozantinib." (PMID 33318047, 2020). "Currently, all clinical trials of first-line ICIs, either single- or dual-agent, have excluded EGFR-mutant and ALK-rearranged lung cancers but included patients with RET-rearranged lung cancers." (PMID 32295619, 2020). "In another study, RET fusions were found in 0.6% (27 out of 4871) patients with different malignancies (besides thyroid and lung carcinoma), including ovarian and salivary gland carcinomas." (PMID 32326537, 2020).
lung cancer (continued). "RET fusions occur in 1%–2% of lung carcinoma, predominantly in adenocarcinoma (LADC) but also in rare types such as adenosquamous carcinoma." (PMID 32326537, 2020). "A brisk and durable ongoing response to LOXO-292 was achieved in a patient with a RET fusion-positive lung cancer who had notable disease progression while receiving a prior multikinase inhibitor and multiple prior stereotactic radiosurgery treatments." (PMID 31485557, 2019). "Alectinib was used to treat four patients with RET positive lung cancer with three patients having received prior RET directed inhibition." (PMID 31058838, 2019). "Lamin B1 loss promotes lung cancer development and metastasis by loss of PRC2 recruitment to chromatin and activation of the RET/p38 signaling axis." (PMID 31015297, 2019). "Other systemic therapy strategies should instead be considered in patients with advanced RET-rearranged lung cancers before administering immunotherapy alone." (PMID 31192313, 2019). "Multikinase inhibitors with activity against RET (eg, cabozantinib or vandetanib) were repurposed to treat patients with RET fusion-positive lung cancers." (PMID 31485557, 2019). "A retrospective assessment of an international registry of American, Asian and European patients assessed the response of 53 RET positive lung cancer patients to various multikinase inhibiting agents." (PMID 31058838, 2019). "Preclinical study suggests a rationale for the use of alectinib as a possible therapeutic option in RET positive lung cancer." (PMID 31058838, 2019). "Given the benefit of pemetrexed-containing regimens in RET-rearranged lung cancers, a combination of a platinum agent, pemetrexed, and pembrolizumab is reasonable to consider." (PMID 31192313, 2019). "Currently, chemotherapy, in particular pemetrexed containing regimes, or clinical trials of targeted therapy remain favoured options for RET positive lung cancer." (PMID 31058838, 2019). "In this article, we describe a patient with a RET fusion-positive lung cancer with brain and leptomeningeal metastases who had an impactful intracranial response to selective RET inhibition with LOXO-292." (PMID 31485557, 2019). "RET was almost undetectable in normal lung tissue and was significantly upregulated in different types of lung cancer." (PMID 31015297, 2019). "This is consistent with other studies reporting low TMB in EGFR, ALK, ROS1, or RET-driven lung cancers [30•], but higher in KRAS or BRAF." (PMID 31172347, 2019). "In this series, we demonstrate that the immunophenotype of RET-rearranged lung cancers is characterized by low levels of PD-L1 expression and low TMB in the majority of patients." (PMID 31192313, 2019). "It is anticipated this agent will be an effective targeted therapeutic option for patients with RET positive lung cancer." (PMID 31058838, 2019). "A phase 2 study of cabozantanib in 26 patients with RET positive lung cancer showed an overall response rate (ORR) of 28%." (PMID 31058838, 2019). "A total of 13 patients with RET-rearranged lung cancers were assessed for clinical and/or radiologic response." (PMID 31192313, 2019). "RET fusions occur in a variety of malignancies, including 1% to 2% of lung cancers and 10% to 20% of papillary thyroid cancers." (PMID 31142054, 2019). "Note that high PD-L1 expression (50% or more) was uncommon in RET-rearranged lung cancers in this study." (PMID 31192313, 2019). "Of note, the truncated isoform of CCDC61–101, involved in the oncogenic fusions to RET or ROS1 kinases in lung cancer, can form heterodimers with and relocate the wild type protein in the cytosol." (PMID 31877762, 2019). "A recommendation regarding the use of pembrolizumab in treatment-naïve, advanced RET-rearranged lung cancers with high PD-L1 expression cannot be made on the basis of our findings, although its use should be approached with caution." (PMID 31192313, 2019).
lung cancer (continued). "The choice of RET for subsequent validation of RTK variants was due to the fact that, at difference with what happens in thyroid and lung cancer, the involvement of RET proto-oncogene to the development of colon cancer is still debated." (PMID 29665843, 2018). "The reasoning for this choice was that, at difference with what happens in thyroid and lung cancer, the involvement of RET proto-oncogene to the development of colon cancer is unclear." (PMID 29665843, 2018). "Recent clinical trials have shown that RET inhibitors are active in a subset of patients with lung cancers harboring RET-rearrangements." (PMID 30446652, 2018). "Recently, however, TK fusions have been identified involving ALK, ROS1 and RET kinases in 3–7, 1–2, and 0.7–2% of lung cancer, respectively." (PMID 29455670, 2018). "An in vitro study showed that apatinib inhibits cellular invasion and migration in lung cancer cells via suppressing RET/Src signaling pathway." (PMID 29029508, 2017). "Several ongoing clinical trials are investigating the effectiveness of tyrosine kinase inhibitors, including vandetanib and sunitinib known for higher specificity to RET, in treating lung cancers with RET rearrangements." (PMID 28460442, 2017). "ALK, ROS1 and RET gene fusions are important predictive biomarkers for tyrosine kinase inhibitors in lung cancer." (PMID 28181564, 2017). "In this paper we utilized three transcriptome-based platforms and compared results with the gold standard of FISH testing for the detection of ALK, ROS1 and RET fusions in lung cancer." (PMID 28181564, 2017). "In a previous report, we detected 15 RET fusion transcripts in cells taken from a lung cancer patient and confirmed five RET fusion partners (KIF5B, CCDC6, TRIM33, NCOA4, and CUX1)." (PMID 27150058, 2016). "In recent studies, lung cancer patients with tumors harboring ROS1 or RET gene fusions have shown notable responses to ALK or other multi-target kinase inhibitors." (PMID 26124082, 2015). "The ongoing phase 2 clinical trial of vandetanib in lung cancer patients harboring RET rearrangement is employing a 300 mg dose and will clear out the efficacy of the drug in this subgroup of patients." (PMID 25884512, 2015). "Phase 2 clinical trials of RET kinase inhibitors in lung cancer patients harboring RET rearrangement are ongoing." (PMID 25884512, 2015). "Sensitivity to vandetanib was also observed in RET-fusion-positive papillary thyroid carcinoma and lung cancer cells." (PMID 26684754, 2015). "An example of this potential approach, defined genomics driven-oncology, is represented by RET rearrangements in lung cancer." (PMID 25884512, 2015). "Together, these studies have identified RET as a potentially important therapeutic target in these subtypes of thyroid, breast and lung cancers." (PMID 25409876, 2014). "MET amplification in lung cancer has recently been shown to be associated with activation of EGFR, ERBB2, ERBB3, and RET." (PMID 23300999, 2013). "We have here shown that MET associates with EGFR, HER2, HER3, and RET, and that these heterodimerisation partners of MET are highly phosphorylated in lung cancer cells positive for MET amplification." (PMID 21847121, 2011). "To examine the roles of MET, EGFR, HER2, HER3, and RET in lung cancer cells with MET amplification, we first investigated the effects of PHA-665752, gefitinib, lapatinib, and vandetanib on cell proliferation and survival." (PMID 21847121, 2011). "It is thus possible that trans-phosphorylated EGFR, HER2, HER3, and RET act as scaffold proteins to promote downstream signalling of MET in lung cancer cells with MET amplification." (PMID 21847121, 2011). "RET fusion-positive lung cancer is rare, accounting for only 1%-2% of all lung cancers." (PMID 40688867, 2025). "In 2012, RET fusions were first identified in lung cancer, with an incidence of merely 1%-2%." (PMID 41018100, 2025).
lung cancer (continued). "Notably, in both this series and prior reports, neuroendocrine carcinomas were the most commonly diagnosed lung cancers with RET fusions, aside from adenocarcinoma." (PMID 38317126, 2024). "The management of lung cancer (LC) requires the analysis of a diverse spectrum of molecular targets, including kinase activating mutations in EGFR, ERBB2 (HER2), BRAF and MET oncogenes, KRAS G12C substitutions, and ALK, ROS1, RET and NTRK1-3 gene fusions." (PMID 38966170, 2024). "It is questionable whether patients with other targetable/driver mutations, such as ROS1 or RET, should be treated with NA ICI-chemo, based on data showing the limited efficacy of immunotherapy in patients with advanced lung cancer who have these mutations." (PMID 38610980, 2024). "Genomic testing revealed an RET fusion-positive lung cancer." (PMID 39272672, 2024). "However, the introduction of selective RET inhibitors (RETis) such as selpercatinib and pralsetinib has significantly improved the prognosis for advanced lung cancer patients with RET fusions." (PMID 38317126, 2024). "RET fusion genes are also seen in other human cancers, such as non–small cell lung cancer." (PMID 38735658, 2024). "Similarly, pralsetinib has shown notable activity in RET fusion-positive lung cancer and RET-mutant MTC." (PMID 39272672, 2024). "Cutaneous adverse events have also been described with treatment-related rashes of all grades developing in 20% and 14.5% of patients with RET-fusion positive nonsmall cell lung cancer and thyroid cancer respectively within clinical trials—though only few with high grade events." (PMID 39148638, 2024). "Therefore, the development of a RET-rearranged lung cancer model would be highly valuable to investigate the unique characteristics of this disease and identify novel therapeutic targets." (PMID 38132167, 2023). "Similarly, combinations with MET inhibitors have induced tumor responses in ALK- and RET-rearranged lung cancers with MET-driven resistance to TKIs targeting the original oncogene drivers." (PMID 37923925, 2023). "Several models of RET-rearranged lung cancer have been developed during previous years." (PMID 38132167, 2023). "It is important to note that other relevant mutations typically associated with lung cancer (such as ALK, ROS1, RET, FGFR1, ERBB2, etc.)have been found with frequencies compatible with previously published data, but without a significant difference between subgroups." (PMID 37173325, 2023). "Given the increasing utilization of selective RET inhibitors in lung cancer patients, these findings call for awareness and guidance of toxicity before initiating treatment with these drugs, as well as monitoring and timely management of AEs during long-term use." (PMID 35838839, 2023). "Diagnosis and treatment process of RET gene fusion non‐small cell lung cancer in China." (PMID 37718634, 2023). "Moreover, there is currently a lack of comprehensive investigation into the efficacy of RET inhibitors in preclinical lung cancer models with RET fusions." (PMID 38132167, 2023). "Vepafestinib inhibited the growth of multiple lung cancer patient-derived cell lines harboring RET fusions with different N-terminal partners (CCDC6, KIF5B, TRIM33) and an RETC634W mutation–positive MTC cell line and was active in a number of NSCLC xenograft models." (PMID 38201460, 2023). "Given that multi-targeted TKIs suppress RET kinase activity, these agents could be considered promising targeted therapies for lung cancer patients harboring RET fusions." (PMID 37686423, 2023). "ALK and RET gene rearrangements are particularly frequent in lung carcinomas." (PMID 37686416, 2023). "This budget may double in the case of NSCLC analysis, because lung carcinomas have to be additionally tested for EGFR, BRAF, KRAS, MET, and HER2 mutations as well as ALK, ROS1, and RET translocations." (PMID 37762506, 2023).